GGT5 (gamma-glutamyltransferase 5)
Diseases named in the same sentence as GGT5 in open-access papers (continued):
Sharing a sentence is not in itself a finding about the gene and the disease.
tumor (continued). "Consequently, attenuating the expression of GGT5 would impede GSH metabolism and enhance anti-tumor capabilities." (PMID 38748299, 2024). "However, the results between GGT5 and tumor stage, N stage, and M stage showed no statistical significance." (PMID 38748299, 2024). "Based on their different expression patterns among normal-tumor-thrombus triples, RAB25 and GGT5 were supposed to play a consistent role in both tumorigenesis and invasion processes, while SHMT2 and CADM4 might play the opposite roles in tumorigenesis and thrombus invasion." (PMID 37328520, 2023). "The results suggested that tadalafil capacity of anti-tumor partially depended on pde5 and its effect on amino acid metabolism also depended on pde5, which was presented by the downregulation of the expression of GPT, GGT5, and TAT in tadalafil treatment with pde5 knockdown groups." (PMID 35694253, 2022). "In addition, IF double-staining with antibodies against GGT5 and α-SMA (a marker of CAFs) in LUAD tissues showed that GGT5 was specifically expressed in CAFs, but not in tumor cells." (PMID 32640421, 2020). "Interestingly, our study clearly confirmed that GGT5 specially expressed in CAFs, but not in tumor cells, which contributed to tumor cell proliferation and drug resistance by increasing intracellular GSH and reducing the intracellular ROS level in LUAD cells." (PMID 32640421, 2020). "However, the expression of GGT5 in primary tumor tissues has not been reported." (PMID 32640421, 2020).
cancer (12 papers, 2019 to 2025). A tumor composed of atypical neoplastic, often pleomorphic cells that invade other tissues. "In the present study, we first reported that high expression of protein GGT5 in cancer-associated fibroblasts (CAFs) predicted the poorer survival of LUAD patients." (PMID 32640421, 2020). "Additionally, we investigated specific mutation types and sites of GGT5 in cancer." (PMID 38581025, 2024). "Subsequently, we utilized the TIMER2 database to investigate the correlation between GGT5 expression and immune cell infiltration levels in pan-cancer." (PMID 38581025, 2024). "Our initial exploration encompassed the expression of GGT5 across diverse cancers, utilizing a comprehensive pan-cancer dataset derived from TCGA and GTEx databases (Genotype-Tissue Expression)." (PMID 38581025, 2024). "Cell growth, foci formation and spheres formation analyses showed that cancer cell proliferation was attenuated under treatment with the conditioned media from GGT5-silenced CAFs." (PMID 32640421, 2020). "Since it has been proved that GGT1 as a member of GGT family was involved in drug resistance, but role of GGT5 during cancer chemotherapy is unclear." (PMID 32640421, 2020). "We first investigated GGT5 expression across cancers in a pan-cancer dataset from TCGA." (PMID 35368661, 2022). "Gamma-glutamyltransferase 5 (GGT5) is expressed in different cancers and its role in cancers remains unclear." (PMID 35257007, 2022). "The study indicated that phase I transcripts, ADH1C and GGT5, phase II NQO2, and phase III SLC25A5 may have diagnostic and therapeutic potential in CRC due to their differential expression in the early phase of this cancer." (PMID 41465541, 2025). "Moreover, high expression of GGT5 in CAFs enhanced the drug resistance of cancer cells by increasing intracellular glutathione and reducing the intracellular reactive oxygen species in cancer cells." (PMID 32640421, 2020). "Compared to case-matched benign tissues, most cases of cancer tissues expressed higher GGT1/GGT5 genes but lower GGT6/GGT7 genes, of which GGT6 expression showed a dramatic reduction in cancer tissues." (PMID 40094020, 2025). "However, GGT5 regulation and its role in cancer remain unclear." (PMID 37328520, 2023). "Differential expressions in the initial stage of cancer (CSI or CSI and CSII), such as for ADH1C, GGT5, NQO2, and SLC25A5 (bolded), may indicate them as candidates for diagnostic biomarkers." (PMID 41465541, 2025). "Indeed, CAF-derived gamma-glutamyl-transferase 5 (GGT5) promotes GSH transfer from the TME to LUAD cells, thereby reducing intracellular ROS levels and inhibiting cancer cell apoptosis." (PMID 36422541, 2022). "GGT5 is a member of the GGT family, but its role in cancer is undefined, especially in LUAD." (PMID 32640421, 2020). "However, GGT1 methylation had no significant alteration and GGT5 methylation was significantly elevated in cancer tissues, which is not in line with the upregulation of GGT5 expression in cancer tissues." (PMID 40094020, 2025). "Given that FAP overexpression may be associated to the inhibition of ferroptosis in cancer cells, we speculate that FAP+ CAFs may inhibit ferroptosis through the effects of GGT5 on GSH and ROS levels, but no related reports have been published." (PMID 36422541, 2022). "Gamma-glutamyltransferase 5 (GGT5) is a member of the gamma-glutamyl transpeptidase gene family with the capacity of cleaving the gamma-glutamyl moiety of glutathione, but its role in cancer progression has never been revealed." (PMID 32640421, 2020). "However, the role of GGT5 in cancer progression have not yet been characterized." (PMID 32640421, 2020). "Therefore, when the conditioned media from GGT5-silenced CAFs was used to treat LUAD cells, less cysteine and glutamate were provided for GSH synthesis in cancer cells, which accounted for the slower cell growth and higher drug-sensitivity of cancer cells after treatment the cultures." (PMID 32640421, 2020).
infection (4 papers, 2016 to 2025). The state of being infected such as from the introduction of a foreign agent such as serum, vaccine, antigenic substance or organism. "On the other hand, certain genes involved in glutathione biosynthesis and recycling (Chac1, Oplah, and Ggt5) were upregulated, highlighting the complex impact of the infection on liver metabolic functions." (PMID 40618034, 2025). "The genes significantly impacted by infection only in CS included mast cell proteinase-3, γ-glutamyltransferase 5 (GGT5), CD163 as well as those involved in smooth muscle contraction, such as tropomyosin (TPM2), myosin, light chain 9, regulatory (MYL9), and calponin 1, basic, smooth muscle (CNN1)." (PMID 27197554, 2016). "Intriguingly, besides GGT5, these proteins all play a role in the defense response against viruses and were completely absent from the EV fraction generated under infection conditions." (PMID 37815349, 2023). "Among the 1,451 genes whose expressions were specifically altered in CEF after infection, some were involved in immune-related functions, while others, such as the significantly upregulated SLBP, P2RX7, GGT5, and RNF213, could promote viral particle replication or enhance the effect of infection." (PMID 38299864, 2024).
GGT5 also shares sentences with these, for which no sentence is quoted: esophageal carcinoma (3 papers); glioblastoma multiforme (3); invasive breast carcinoma (3); kidney chromophobe (3); prostate adenocarcinoma (3); uterine corpus endometrial carcinoma (3); cervical squamous cell carcinoma (2); colon cancer (2); endocervical adenocarcinoma (2); head and neck squamous cell carcinoma (2); paraganglioma (2); pheochromocytoma (2); bladder urothelial carcinoma (1); breast tumor (1); cardiovascular diseases (1); endometriosis (1); hepatocellular carcinoma (1); thymoma (1).